CD4 (CD4 molecule)
Diseases named in the same sentence as CD4 in open-access papers (continued):
Sharing a sentence is not in itself a finding about the gene and the disease.
cancer (continued). "Studies of infiltrating CD3, CD4, CD8, FoxP3, or CD25 positive cells and the CD4:CD8 ratio in the epithelium, stroma, or total tissue of normal, lgCIN, hgCIN, or cancer were abstracted for inclusion in the review." (PMID 33257839, 2021). "In our study, there was obviously positive correlation between CD4/CD3 and Ki-67 in primary cancer and negative correlation between CD4/CD3 and ER in oligometastatic cancer." (PMID 34858823, 2021). "With regard to the primary lesions, the densities of CD4+ T-cells, CD8+ T-cells, CD204+ cells, and CD4+Foxp3+ T-cells in carcinoma and stromal areas were not statistically correlated with OS by linear regression models." (PMID 34647108, 2021). "At present, the biological functions of cancer-related CXCR7+ immune cells have not been intensively studied, but we found that the expression of CXCR7 was related to CD8+ T cell, CD4+ T cell, neutrophil and dendritic cell in ccRCC microenvironment." (PMID 33324682, 2020). "Cancer cell-derived exosomes expressing TGF-β can downregulate NKG2D expression on NK and CD8+ T cells, while other receptors, including CD4, CD8, CD56, CD16, CD69, and CD94 are not affected, indicating the selectivity of the effect." (PMID 31948072, 2020). "These lymphocyte subpopulations were of similar size within both CD4 and CD8 cells, which indicated the absence of systematic T cell exhaustion in either cancer groups." (PMID 31090020, 2020). "CD4, CD8, and CD16 were not significantly correlated to ANAM neuropsychological performance for the cancer survivor comparison group of women." (PMID 32434503, 2020). "As expected, separated CD4+ and CD8+ T cells were fully functional to recognize cancer cells to produce IFN-γ when they were transduced by 19305DP-TCR, whereas only CD8SP-TCR-transduced CD8+ T cells but not CD4+ T cells were reactive against cancer cells." (PMID 30626427, 2019). "The CCI was extremely positively correlated with activated dendritic cell in GBM and LIHC, activated mast cell in PRAD, plasma cell in GBM, and resting memory CD4 T cell in LIHC, and these correlations were either weaker or negative in other cancers." (PMID 30791227, 2019). "S3 Fig shows the frequency of CD4+ and CD8+CD45RC in patients that did not developed cancer or AR (n = 48), and those that developed cancer (n = 16), AR (n = 23) and both (n = 2)." (PMID 30925186, 2019). "A rare population of NY-ESO-1-specific T cells, which we named 19305DP, expressed cell surface CD4, CD8α, and CD8β but not CD56 and recognized A*02+NY-ESO-1+ cancer cell lines in a CD4- and CD8-independent manner." (PMID 30626427, 2019). "Before coculture, cancer cells or T cells were incubated with or without (−) anti-MHC class I (αHLA-A,B,C), anti-CD4 (αCD4) or anti-CD8 (αCD8) antibody for 30 min and then T cells or cancer cells were added without washing out the antibodies." (PMID 30626427, 2019). "The viSNE plots of the main subsets in blood samples show the absence of peripheral CD4+, CD8+ T-, and B-cells and the emergence of CD11b+ cells as a sign of advanced cancer compared to naive blood." (PMID 31881770, 2019). "These alterations in DP T-cell frequencies were not owing to a variation in CD4+ or CD8+ single positive T-cells as their frequency were similar between HD and cancer patients." (PMID 30984190, 2019). "Frequency of CD4+CD45RChigh, as well as those of CD8+CD45RChigh, were significantly lower in patients with cancer as compared to patients without cancer." (PMID 30925186, 2019). "Split tolerance to GUCY2C in cancer patients can be exploited to safely generate antigen-specific cytotoxic CD8+, but not autoimmune CD4+, T cells by Ad5-GUCY2C-PADRE in the absence of pre-existing NAbs to the viral vector." (PMID 31010434, 2019). "The CyTOF analysis revealed the emergence of CD11b+/Gr-1+/CD44+ or CD11b+/Gr-1+/IL-17A+ myeloid-derived suppressor cells (MDSCs) and the absence of B220+ or CD62L+ B-cells, the CD62L+/CD4+ and CD62L+/CD8+ T-cells in the spleen of advanced cancer." (PMID 31881770, 2019).
cancer (continued). "Both LLC-NT and LLC-sh21 cancer cells expressed MHC class I but had low levels of MHC class II expression, suggesting selective interactions with CD8+, but not CD4+ T cells." (PMID 31133614, 2019). "Whether the enhancement of CD4 T-cell immunogenicity in the absence of strong CD8 T-cell immunogenicity leads to better vaccine (i.e. in the case of TB) or immunotherapeutic (i.e. in the case of a carcinoma) outcomes warrants testing in disease-specific animal models." (PMID 30842561, 2019). "Blocking the PDL1 pathway significantly increased the proliferation of allogeneic CD4+ T cells, suggesting that the PDL1 upregulation in cancer cell line exposed- (but not mf-exposed) monocytes plays an important role in T cell suppression." (PMID 29668679, 2018). "Since CD4+ and CD8+ T cells do not express OCTN1, it is possible that an STDME diet preferentially eliminates ROS production from MDSCs and cancer cells without directly affecting T cell-dependent antitumor activity." (PMID 30262787, 2018). "In a different setting than cancer, activated T cells with high CD39 expression were prone to apoptosis in older individuals and suggested that CD4+CD39+ effector T cells do not develop into long-lived memory cells." (PMID 28388539, 2017). "T (CD3; both CD4 and CD8 although data not shown) and B lymphocytes and CD11b positive myeloid cells accumulated in the Hi-Myc mouse prostates in concert with cancer development." (PMID 29212195, 2017). "As shown by flow cytometry almost complete absence of B cells, markedly reduced number of T cells, CD4+ and CD8+ T cell subsets and Natural killer (NK) cells were demonstrated before the patient’s first cancer diagnoses." (PMID 28720148, 2017). "Cancer tissue had increased immune cell infiltration with recruitment of CD163+ (M2 macrophage), CD25+ (regulatory T lymphocyte), and CD4+ (T helper) cells compared to non-cancer tissue." (PMID 26964534, 2016). "Also, recent findings suggest that a fusion construct consisting of a cancer antigen (NY-ESO-1) with proteins targeting the cancer antigen for autophagic degradation could assist in epitope expression by MHC II and enhancement of CD4+ T cell-mediated antitumor responses." (PMID 27896219, 2016). "Taken together, our data indicate that the CD4+ and CD8+ T cell infiltrate, similarly to PD-1+ and PD-L1+ T cells is not regulated by PD-1 or PD-L1 expression in cancer cells but rather is proportional to the amount of T cell infiltration in general." (PMID 26625204, 2016). "Positive for cancer progression; CD4+ and CD8+ cells were increased in cancer vs. non-atrophic benign tissue, but did not correlate with Gleason Score." (PMID 26217583, 2015). "FOXP3 expression has been recently described in normal cells and in non-hematopoietic-derived cancer cells, suggesting that FOXP3 biological effects are not restricted to Foxp3+CD4+ T cells." (PMID 26604855, 2015). "GEM has the potential to augment the antitumor effects of cancer immunotherapy by suppressing Treg induction, and also reduces MDSC, but does not reduce CD4+ T cells, CD8+ T cells, NK cells, macrophages, or B cells." (PMID 24947606, 2014). "For example, the finding may reflect bias that may be introduced if patients with lower CD4 counts were not offered, or could not tolerate anti-cancer treatments (we have limited data on use of chemo- and/or radio-therapy, or on surgical treatments for cancer)." (PMID 24106926, 2013). "While CD8+ Tregs are not as well studied as their CD4+ Treg counterparts, both CD8+ nTreg and iTreg have been identified and characterized, including reports in individuals with cancer." (PMID 24151492, 2013). "Despite the fact that we observed no prognostic significance of high CD4+ T-cell infiltration alone, we found a synergistic effect of simultaneous high CD4+ T-cell and CD8+ T-cell infiltration in cancer stroma as a favourable prognostic factor in NSCLC." (PMID 16421594, 2006).
cancer (continued). "Part of the explanation for this could be that Tregs are able to directly suppress not just CD4+ helper T cells and CD8+ cytotoxic T cells, but also NK cells after cancer treatment." (PMID 40226609, 2025). "Additionally, a relatively immunologically “cold” TME in HRASmt TNBC and UC was observed, as demonstrated by decreased CD4+ and CD8+ T cells in each cancer type, although none of these differences reached statistical significance." (PMID 38672653, 2024). "We were thereby able to show a positive correlation between BTN3A1, MAP3K3, and UBA7 expression and the majority of immune infiltrates (B cells, CD4 + T cells, CD8 + T cells, macrophages, and neutrophils) in most cancer types, and a negative correlation with myeloid dendritic cells." (PMID 39127727, 2024). "Variations were observed in the proportion of monofunctional CD4 T cells producing TNF, particularly higher in individuals without cancer and patients treated with chemotherapy alone, while those treated with immunotherapy or chemoimmunotherapy predominantly produced IFNγ." (PMID 39257577, 2024). "Importantly, the type of cancer treatment including anti-CD20 agents and BTKi did not affect the S-specific memory CD4+ and CD8+ T lymphocyte response." (PMID 39339993, 2024). "In total, 11 569 individuals had no CD4 and CD8 cell counts or viral load measurements recorded after January 2012, never started ART, or had < 12 months follow-up and were excluded, leaving 19 247 individuals and 730 malignancies for analysis." (PMID 38092042, 2024). "Current data from PWH on ART with cancer who receive anti‐PD‐1, report a similar frequency of adverse events in this population compared to people without HIV, with this frequency not affected by CD4+ T‐cell count." (PMID 39248154, 2024). "Nevertheless, whether CD4+T cells also play a role in HCC immune surveillance and how cancer cells suppress CD4+T cell function was not well studied." (PMID 38956432, 2024). "Furthermore, unlike CD4 LAG‐3 restrains T cell responses and antibodies targeting this receptor are emerging drugs in cancer immunotherapy." (PMID 39560030, 2024). "When tested on primary human lymphocytes activated with αCD3/28 beads ± rhIL2, pevonedistat demonstrated a negative impact on the proliferation of CD4+ T cells, CD8+ T cells and NK cells with comparable potencies as observed in cancer cells, i.e., between 100 nM and 600 nM." (PMID 38678024, 2024). "Last, to determine whether DPTs lacked GVL activity because they developed independent of human B-ALL cancer antigens, we repeated this experiment with isolated CD8 T cells and depleted the DPT population using a mouse anti-human CD4 antibody." (PMID 36961891, 2023). "Furthermore, the expression of CXCL 13 was positively correlated with CD8+ T cell percentage in most cancers, while the correlation between CXCL13 expression with CD4+ T cell and NK cell was not identified." (PMID 37540227, 2023). "Most TCRs were identified as T cells rather than cancer cells or B cells, among which CD4+ and CD8+ T cells had the highest percentages while the CD4- and CD8- (double negative, DN T cell) carried the lowest TCRs, suggesting the maturity and function complexity of T cells." (PMID 37889543, 2023). "Using this approach, they discovered that unlike CD4+ and CD8+ cells that were coherently spread in the tissue, regulatory T cells were meaningfully present only in the stromal cancer tissue with minimum presence in the epithelial compartments, at both cancer and normal sides." (PMID 37091793, 2023). "Finally, we assessed expression of TMEM123 by FACS analysis in CD4+ and CD8+ T lymphocytes isolated ex vivo from paired cancerous and non-tumoral tissue samples (proximal, but not adjacent to cancer cells) (N=14) and from peripheral blood (N=11)." (PMID 37426665, 2023).
cancer (continued). "Previous studies have not always separated MAIT cells into subsets based on CD4 and CD8 expression, which may partially explain some discrepancies regarding the role of MAIT cells in cancer." (PMID 35028137, 2022). "We further detected the CD4+ IFNAR1 levels and CD8+ PD1 levels of peripheral blood lymphocytes in 15 patients with VPS9D1-AS1 positive expression and 16 patients with VPS9D1-AS1 negative expression in cancer tissues." (PMID 36458816, 2022). "In vitro coculture of control HPAF-II cancer cells with nonadherent human PBMCs significantly suppressed the CD3/CD28-induced proliferation of both CD8 and CD4 T cells, and also reduced levels of IFNγ and GMCSF, cytokines important in generating an active antitumor immune response." (PMID 36922934, 2022). "However, such an obvious positive correlation was not seen in B cells, CD4+ T cells, CD8+ T cells, and dendritic cells, especially in DLBC, HNSC, TGCT, and THYM; the trend of this correlation was slightly different, which may be caused by different immune cell infiltration in different cancers." (PMID 36159856, 2022). "Furthermore, there were negative correlations between cancer and the lymphocyte counts and T cell subset, between CHB and the lymphocyte counts and T cell subset (especially CD3+CD4+),and between CKD and the CD3+ counts." (PMID 35865540, 2022). "In the aspect of immune infiltration levels, BSG expression showed a negative correlation with nearly all six types of immune cells (B cells, CD4+ T cells, CD8+ T cells, neutrophil, macrophage, and dendritic cells) in THCA, CHOL, and SKCM (p < 0.05) rather than other cancers." (PMID 35646943, 2022). "Moreover, positive PD-L1 carcinomas exhibited greater infiltration of all evaluated TIL subtypes in comparison to negative PD-L1 cases: CD3+ (25% vs. 10%; p < 0.001), CD4+ (20% vs. 10%; p < 0.001) and CD8+ (10% vs. 5%; p < 0.001)." (PMID 36139578, 2022). "CD4+ T cells co-cultured with MDA-MB-231 cancer cells during the restimulation period exhibited substantially increased proportion of CD274+ and CD273+ T cells in comparison to lymphocytes restimulated in the absence of cancer cells." (PMID 34439305, 2021). "Despite increasing evidence for the safety and efficacy of ICIs for PLWH, 74.4% of recent cancer ICI trials excluded all PLWH regardless of patients’ viral loads, CD4+ T-cell counts, or HIV treatment courses, limiting treatment options for cancer patients with HIV." (PMID 33758321, 2021). "In addition, ROR1 showed a moderate negative correlation with activated CD4+, neutrophils, and natural killer T (NKT) cells in a few cancer types." (PMID 34319035, 2021). "However, the roles of CD4 and CD8 single-positive T cells in TETs have not yet been elucidated in detail from the aspect of cancer immunology." (PMID 32132638, 2020). "IL-30-silenced tumors developed in IL-30KO mice, IL-30−/−tumors, lacked vascular supply and displayed frequent apoptotic cancer cells entrapped by perforin+TRAIL+CD3+Tlymphocytes, most of which had a CD4+T phenotype, whereas IL-10+TGFβ+Foxp3+Tregs were lacking." (PMID 31366386, 2019). "In accordance with this, we found that the single blockade of PD-L1 or in combination with PD-1 did not have any beneficial effects on activated CD4+CD25+ T cells but, in fact, further increased the expression of alternate ICs, such as TIM-3 and LAG-3 (new emerging therapeutic targets for cancer)." (PMID 31614877, 2019). "Moreover, both these carcinomas showed high infiltration of CD8+ T cells and dendritic cells but not B cells or CD4+ T cells." (PMID 30775178, 2019). "DC-based HHP cancer vaccine alone or in combination with chemotherapy was shown to significantly inhibited growth of tumors in mouse models, however the differential contribution of CD8+ or CD4+T cells was not analyzed." (PMID 28187172, 2017).
cancer (continued). "In addition to CSF1, IL-4 from CD4+ T cells is necessary to activate TAMs to produce EGF and without CD4+ T cells, TAMs are unable to induce cancer cell migration and metastasis." (PMID 29220404, 2017). "Despite a CD4+ bias, there was no increase in CD4+ CD25+ CD27− FoxP3+ Tregs, which may have a negative effect on anti-cancer potency of adoptively transferred T cells." (PMID 28239467, 2017). "The pathway, ‘Molecular Mechanism of Cancer’, was found to be altered for the microRNAs that correlated with the presence of CD3+, CD45+, CD8+, and CD68+ lymphocytes as well as infiltrating adipocytes, but not CD4+ lymphocytes." (PMID 28145100, 2017). "The combined CpG-ODN/LL-37 therapy, expression of interferon (IFN)-γ, inducing proliferation and activation of natural killer (NK) cells, but not CD4+ or CD8+ T cells, in the peritoneal cavity, ultimately increase the organism’s natural defenses against the cancer cells." (PMID 26395996, 2016). "CD4+ Th cells are required for activation and maintenance of CD8+ CTLs, but they could also exert cytotoxic function against cancer in the absence of CD8+ CTLs recognizing antigenic peptides presented by MHC class II molecules." (PMID 24589652, 2014). "Interestingly, TIM-3 expression on CD4+ T cells but not CD8+ T cells correlated with poor clinicopathological parameters of NSCLC such as nodal metastasis and advanced cancer stages." (PMID 22363469, 2012). "However, most cancer cells are MHC class II negative and therefore cannot be directly recognized by CD4+ T cells." (PMID 22649466, 2012). "Additionally, because CD4+ T cell responses may not be as central to ICI antitumor efficacy, they might be therapeutic targets to reduce IrAEs in patients with cancer while preserving efficacy." (PMID 40626363, 2025). "Moreover, we have also not tested whether the secretome of cancer cell – CAF co-culture has any effect on other immune cells, i.e., CD8+ T cells, CD4+ T helper cells, T regulatory cells." (PMID 39262776, 2024). "Specifically, in co-cultures with rSFV-infected LNCaP and PANC-1 cells, CD4 and CD8 T cells were found to exhibit a pro-inflammatory profile represented by an increased expression of the activation markers CD69 and CD107 compared to controls with non-infected cancer cells (NT)." (PMID 38425844, 2024). "In addition, these results indicate that not all PC-EVs are able to induce early CD4+ and CD8+ activation, which may be relevant in experimental strategies aimed at inducing antitumor immune responses using cancer-EV treatment." (PMID 38791876, 2024). "Moreover, the population of CD4+CD25+Foxp3+ Tregs and Gr1+CD11b+ MDSCs was not increased by RT plus iPSC-based cancer vaccines, indicating that this therapeutic strategy might not induce Treg-mediated suppression of TAA-reactive T cells." (PMID 38821980, 2024). "Therefore, we investigated whether the lack of Ku70 affects CD4+ and CD8+ T cells during the development of intestinal inflammation and cancer." (PMID 38277448, 2024). "Furthermore, an analysis of the relationship between infiltration estimation and gene expression in gene modules revealed that T-cell CD4+ Th1 in genes ERRFI1, ZBED5, UQCRC2, ZNF146, ABHD17A, YWHAZ, and especially PLSCR4 showed a negative correlation in nearly 40 types of cancer." (PMID 38464509, 2024). "However, in most cancer types, a negative correlation was observed between high R3HDM1 levels and the recruitment of CD4+T cells (step 4), recruitment of CD8+T cells (step 4), and immune cell infiltration into tumors (step 5), further indicating the immunosuppressive role of R3HDM1 in the TME." (PMID 39376739, 2024). "The CD4+ T cells obtained from two different healthy donors were polyclonally stimulated with anti-CD3/CD28/CD2 moAb-coated beads and with IL-2 for 12 days, then subsequently polyclonally restimulated for next 3 days without IL-2 in the presence or without MDA-MB-231 cancer cells." (PMID 34439305, 2021).